LNX1 (ligand of numb-protein X 1)
Description:
E3 ubiquitin-protein ligase that mediates ubiquitination and subsequent proteasomal degradation of NUMB. E3 ubiquitin ligases accept ubiquitin from an E2 ubiquitin-conjugating enzyme in the form of a thioester and then directly transfers the ubiquitin to targeted substrates. Mediates ubiquitination of isoform p66 and isoform p72 of NUMB, but not that of isoform p71 or isoform p65. Isoform 2 provides an endocytic scaffold for IGSF5/JAM4.
Synonyms: LNX; PDZRN2; MPDZ
Tractability: No criterion of Open Targets' tractability assessment is met for any kind of drug.
Gene: Protein-coding gene on chromosome 4 (53,459,301 to 53,701,405, reverse strand). Ensembl gene ENSG00000072201.
Subcellular location: Cytoplasm
Subcellular location (Human Protein Atlas): Cell Junctions; Cytosol
Pathways (Reactome):
Immune System: Antigen processing: Ubiquitination & Proteasome degradation
Gene Ontology:
Molecular function: identical protein binding; protein binding; ubiquitin-protein transferase activity; metal ion binding; PDZ domain binding; ubiquitin protein ligase activity
Biological process: ubiquitin-dependent protein catabolic process; protein ubiquitination; synapse maturation
Cellular component: cell junction; cytosol; cytoplasm; hippocampal mossy fiber to CA3 synapse; postsynapse
Genetic constraint (gnomAD): Loss-of-function variants: 52 observed, 69.88 expected, observed/expected ratio (o/e) 0.74, 90% interval 0.6 to 0.94. The upper end of that interval is the gene's LOEUF score, 0.94, which puts it in group 3 of 6, group 1 being the genes least tolerant of losing a copy. Missense variants: 895 observed, 956.7 expected, observed/expected ratio (o/e) 0.94, 90% interval 0.88 to 0.99. Synonymous variants: 331 observed, 365.32 expected, observed/expected ratio (o/e) 0.91, 90% interval 0.83 to 0.99.
Homologues: Orthologues: chimpanzee LNX1 (99% identical), macaque LNX1 (98% identical), pig LNX1 (90% identical), dog LNX1 (89% identical), mouse Lnx1 (88% identical), rat Lnx1 (87% identical), guinea pig LNX1 (77% identical), rabbit LNX1 (70% identical), tropical clawed frog lnx1 (64% identical), zebrafish lnx1 (60% identical), Caenorhabditis elegans frm-5.1 (11% identical), Caenorhabditis elegans frm-5.2 (11% identical). Paralogues in human: LNX2 (47% identical), MPDZ (27% identical), PATJ (27% identical), FRMPD2 (17% identical), STXBP4 (10% identical).
Diseases named in the same sentence as LNX1 in open-access papers:
LNX1 is named in the same sentence as 21 diseases in open-access papers, as found by Europe PMC text mining. Sharing a sentence is not in itself a finding about the gene and the disease. The quoted sentences say what the papers report.
Anxiety (5 papers, 2017 to 2025). Intense feelings of nervousness, tension, or panic often arise in response to interpersonal stresses. "The underlying basis for the distinct anxiety-related and risk-taking behavioural phenotypes of Lnx1−/− and Lnx2−/− mice at the molecular and neural circuitry level are not immediately obvious." (PMID 40269869, 2025). "Here, building upon these previous studies, we performed a detailed analysis of stress, anxiety, risk taking and ultrasonic vocalisations in Lnx1-/- and Lnx2-/- single and double knockout animals of both sexes." (PMID 40269869, 2025). "Overall, the results of the dark-light emergence and wire beam bridge tests clearly demonstrate decreased anxiety-related or increased risk-taking behaviour in Lnx1−/−;Lnx2−/− mice and suggest a more prominent involvement of Lnx2 versus Lnx1 knockout in causing this phenotype." (PMID 40269869, 2025). "Here we significantly extend this work by examining anxiety-related and risk-taking behaviours in Lnx1-/- and Lnx2-/- single knockout animals for the first time and by analysing previously unexplored aspects of behaviour in both single and double knockout animals." (PMID 40269869, 2025). "In terms of molecular mechanisms, the disruption of a LNX1-GluN2B-EphB2 ternary complex within CA3 that has been proposed to underlie defects in social memory in a different line of Lnx1 null mice, might also play a role in changes in the anxiety-related phenotypes that we observed." (PMID 40269869, 2025). "The main behavioural alteration observed in these Lnx1-/-;Lnx2-/- double knockout animals was decreased anxiety-related behavior in the open field and elevated plus maze paradigms." (PMID 40269869, 2025). "In summary, the analysis presented here delineates for the first time distinct roles for LNX1 and LNX2 proteins in regulating anxiety-related and risk-taking behaviour, ultrasonic vocalizations and body weight." (PMID 40269869, 2025). "Overall, these observations pinpoint the specific roles of LNX1 and LNX2 proteins in modulating certain aspects of anxiety and risk-taking behaviour and social communication in mice." (PMID 40269869, 2025). "The most notable findings were decreased anxiety-related behaviour in the elevated plus maze for both males and females, and in the open field arena for male Lnx1−/−;Lnx2−/− mice." (PMID 40269869, 2025). "Both the dark-light emergence and wire beam bridge tasks revealed significant changes in parameters indicative of either decreased anxiety or increased risk-taking for Lnx2−/− and Lnx1−/−;Lnx2−/−, but not Lnx1−/− mice." (PMID 40269869, 2025). "We previously observed decreased anxiety-related behaviour in Lnx1-/-;Lnx2-/- double knockout mice in the elevated plus maze test, which is based on rodents’ preference to explore and spend time in the “safer” environment of the closed, versus the open arms of the maze." (PMID 40269869, 2025). "In agreement with a role for LNX proteins in regulating neural development, double knockout mice lacking both LNX1 and LNX2 in the central nervous system exhibit reduced anxiety-related behaviour." (PMID 29121065, 2017). "Knockout LNX1 and LNX2 mice exhibited decreased anxiety-related behavior, though the mechanisms remained unknown." (PMID 33371872, 2020). "Twenty years on from their initial discovery, I discuss here the putative neuronal functions of LNX1/2 proteins in light of the anxiety-related phenotype of double knockout mice lacking LNX1 and LNX2 in the central nervous system (CNS)." (PMID 32714586, 2018). "The decreased anxiety-related behaviour seen for double knockout animals in the open field and elevated plus maze tests was reproduced and it was found that the absence of both Lnx1 and Lnx2 is required to observe a robust phenotype in these tests." (PMID 40269869, 2025). "We previously reported that mice lacking both LNX1 in the central nervous system and LNX2 globally exhibit decreased anxiety-related behaviour." (PMID 40269869, 2025).
glioma (5 papers, 2017 to 2021). A benign or malignant brain and spinal cord tumor that arises from glial cells (astrocytes, oligodendrocytes, ependymal cells). "Over and above the plausible tumor-suppressive roles of LNX1 in glioma development, various missense mutations in LNX1 have been frequently observed in neurological tumors in humans." (PMID 33333989, 2020). "Furthermore, several studies associated with cancer and LNX1 have suggested its role as a tumor regulator in various cancers, including gliomas and colorectal carcinoma." (PMID 34439220, 2021). "In glioblastoma, LNX1 regulates Notch1 signaling and induces expansion of the glioma stem cell population." (PMID 34439220, 2021). "The tumorigenic roles of LNX1 have also been observed in other cancer tissues, including gliomas, nervous system tumors, and epithelial-like tumor cells." (PMID 33333989, 2020). "As Notch has been established as a critical signaling hub for glioma progression, we next set out to examine the effect of LNX1 elevation after TMZ therapy on this axis." (PMID 33255632, 2020). "However, considering that gene amplification at the chromosome level does not always correlate with increased transcription, the reduced expression level of LNX1 in gliomas may have simply resulted from genetic instability at locus 4q12, where LNX1 is located." (PMID 33333989, 2020). "Up-regulated genes included the glioma related genes SEC61G and LNX1 and the cell cycle related SERTAD1 and CCNH." (PMID 29163818, 2017). "However, it has not been analyzed whether the progression of glial tumors is contingent upon the altered amino acid sequences in LNX1 (A227V and R428H)." (PMID 33333989, 2020). "Down-regulation of LNX1 mRNA was noted in gliomas compared with healthy brain tissue, though this might reflect the fact that LNX1 and LNX2 mRNA are expressed predominantly in neurons and as such would be present at lower levels in gliomas that are derived from glia." (PMID 32714586, 2018).
glioblastoma (4 papers, 2018 to 2022). The most malignant astrocytic tumor (WHO grade IV). "Our work shows that one of the genes altered is LNX1, which increases the expression of Notch1, a gene important for glioblastoma progression." (PMID 33255632, 2020). "Finally, we showed that forced reduction in LNX1 expression results in increased survival of animals implanted with glioblastoma." (PMID 33255632, 2020). "Interestingly, a previous study of cancer stem cells in glioblastoma reported LNX1 mRNA to be up-regulated in CD133− compared with CD133+ stem cells, suggesting that an involvement of LNX1 in cancer stemness may not be specific to CRC." (PMID 32714586, 2018).
colorectal cancer (3 papers, 2017 to 2025). A primary or metastatic malignant neoplasm that affects the colon or rectum. "By exploring the underlying molecular mechanisms, it was found that LNX1 suppresses cancer stemness which partially requires the CXADR interference in colorectal carcinoma." (PMID 29190716, 2017). "For instance, For example, LNX1 has been identified as a negative regulator of cancer stem-like cells (CSCs), playing a significant role in regulating the stemness of colorectal cancer cells." (PMID 39968416, 2025). "It was also demonstrated that the expression of LNX1 was downregulated in colonospheres or SP of colorectal carcinoma cells." (PMID 29190716, 2017). "Besides, it was also observed that the level of CXADR was negatively correlated with the level of LNX1 in various colorectal carcinoma cell lines." (PMID 29190716, 2017). "Here we identified LNX1 as a new negative regulator of cancer stemness in colorectal carcinoma." (PMID 29190716, 2017). "Thus, LNX1 was identified as a negative regulator of cancer stemness in colorectal carcinoma." (PMID 29190716, 2017). "Both LNX1 and LNX2 can be detected directly by Western blotting in colorectal cancer (CRC) cell lines but their detection in other cell lines has not been widely reported." (PMID 32714586, 2018). "In addition, colonosphere formation assay and ELDA analysis reveal that tamoxifen could inhibit the capacity of colonosphere formation and decrease the sphere formation rates in the presence of LNX1, which demonstrated it as a potential target for colorectal carcinoma therapy against CSCs." (PMID 29190716, 2017). "By detecting RNA level of LNX1 of the sorted SP and non-SP from the colorectal carcinoma cell line HT29, it was found that LNX1 was highly expressed in SP cells with higher levels of LGR5, ABCB5, ALDH1A1 and CD133 rather than non-SP group." (PMID 29190716, 2017). "I also review what is known about non-neuronal roles of LNX1/2 proteins, including their roles in embryonic patterning and pancreas development in zebrafish and their possible involvement in colorectal cancer (CRC), osteoclast differentiation and immune function in mammals." (PMID 32714586, 2018). "Moreover, depletion of CXADR could not abolish the function of LNX1 in regulating cancer stemness, indicating there may be other downstream substrates of LNX1 in colorectal carcinoma." (PMID 29190716, 2017).
breast carcinoma (2 papers, 2017 to 2025). "Noteworthy, the E3 ubiquitin ligase LNX1 localizes at the membrane of breast cancer in HPA, and has been shown to mediate the degradation of the PBK by the UPS." (PMID 39984471, 2025). "By exporting the GEO profile of LNX1, it was observed that LNX1 was downregulated in ERα-silenced breast cancer cells." (PMID 29190716, 2017). "Interestingly, the anti-breast cancer drug tamoxifen was found to be an agonist of LNX1 and suppress cancer stemness in CRC." (PMID 29190716, 2017). "That is, LNX1 could not be significantly upregulated by tamoxifen in the absence of ER in breast cancer." (PMID 29190716, 2017).
lung carcinoma (2 papers, 2019 to 2024). "LDOC1 interacts with Ligand-of-Numb protein X1 (LNX1), an E3 ligase, to induce Janus kinase 2 (JAK2) ubiquitination and degradation, which negatively regulates STAT3 activation and IL-6 secretion in lung cancer cells." (PMID 39682774, 2024).
autism spectrum disorder (1 paper, 2022). A spectrum of developmental disorders that includes autism, and Asperger syndrome. "Besides the EphB receptor, Lnx1 involved a protein interaction network of postsynaptic compartments and of alternatively spliced isoform that links genetic risk factors for autism spectrum disorders." (PMID 35531068, 2022).
brain tumours (1 paper, 2018). "By contrast, other reports demonstrate amplifications of a chromosomal region (4q12) containing the LNX1 gene in brain tumours and osteosarcoma xenografts." (PMID 32714586, 2018). "A number of reports have highlighted altered LNX1 expression in the context of brain tumours, although in most cases a causative role for LNX1 in driving tumorigenesis has not been demonstrated." (PMID 32714586, 2018).
cognitive defects (1 paper, 2021). "Through gene targeting we find that Lnx1 deficiency led to a hippocampal subregional disorder in neuronal activity and social memory impairments for partner discrimination observed in juvenile mice which also show cognitive defects in adult stage." (PMID 31772302, 2021).
colon cancer (1 paper, 2017). "In sum, this study provided the evidences that LNX1 signaling plays important roles in regulating the stemness of colon cancer cells." (PMID 29190716, 2017).
developmental delay (1 paper, 2025). "Thus it is possible that differences in USVs are reflective of differences in body weight and a general developmental delay in Lnx1−/− and Lnx1−/−;Lnx2−/− mice that could, for example, cause altered laryngeal morphology or ability to control breathing with consequent changes in USVs." (PMID 40269869, 2025).
Kawasaki disease (1 paper, 2018). A rare inflammatory disease characterized by an acute febrile, systemic, self-limiting, medium-vessel vasculitis primarily affecting children. "A GWAS found intronic SNPs in LNX1 that are associated with susceptibility to Kawasaki disease—an inflammatory paediatric condition that causes damage to the corony arteries and is thought to be triggered by an unidentified infection." (PMID 32714586, 2018). "This study also noted differences in whole blood LNX1 transcript levels in acute compared with convalescent Kawasaki disease." (PMID 32714586, 2018).
Lissencephaly (1 paper, 2022). A spectrum of malformations of cortical development caused by insufficient neuronal migration that subsumes the terms agyria, pachygyria and subcortical band heterotopia. "The data suggest that pathological activation of LNX1 and RhoC contributions to a lissencephaly phenotype may be the consequence of reduced LIS1 protein levels rather than missense-dependent disruption of LNX1-LIS1 specific binding." (PMID 36192543, 2022). "At the same time, the H149R mutation in LIS1 that causes the most severe lissencephaly phenotype among missense mutations, destabilizes LIS1 to reduce its level, but does not disrupt the ability of LIS1 to bind LNX1." (PMID 36192543, 2022).
mental disorder (1 paper, 2020). A disease that has its basis in the disruption of mental process. "The first was for the ST2-SC (CTNNB1) and the second was for ST3-TP (LNX1), indicating these two genes might be involved in the pathogenesis of five mental disorders during these two spatiotemporal points." (PMID 33371872, 2020).
Q fever (1 paper, 2018). A bacterial infection caused by Coxiella burnetii. "The authors suggest that LNX1/2 expression could be used as a prognostic biomarker in Q fever patients." (PMID 32714586, 2018). "A different report found that blood levels of both LNX1 and LNX2 mRNAs were significantly elevated in chronic compared with acute Q fever." (PMID 32714586, 2018).